ENSG00000280371 ( gene)
Diseases named in the same sentence as ENSG00000280371 in open-access papers (continued):
Sharing a sentence is not in itself a finding about the gene and the disease.
tumor (continued). "Finally, we illustrated that the effect of AOX1 as a tumor suppressor gene is not restricted to ccRCC but universally exists in many other cancer types." (PMID 34290740, 2021). "The mitotic checkpoint gene, BUB1, may also drive tumor metastasis and progression." (PMID 26096802, 2015). "Notably, MT1G could not be simply identified as a tumor suppressor gene or oncogenic gene in ccRCC, but MT1G seemed to play a dual role in the development and progression of tumors." (PMID 36204178, 2022). "However, the reduced expression level of CAV1 in EOC cells compared to noncancerous tissues may point to a role for CAV1 as a tumor suppressor gene." (PMID 32401768, 2020). "In our research, the reduction in expression levels of WISP1 was observed in the TS group compared with the NS group, which suggested that WISP1 may act as a tumor suppressor gene in MD-induced tumorigenesis, unlike its oncogenic role in many kinds of human cancers and cell lines." (PMID 30922224, 2019). "However, because the available probe in the validation set proved to be not specific to PTEN, we could not confirm its frequent involvement as a tumor suppressor gene in this set." (PMID 25551557, 2014). "Furthermore, Notch mutation study of head and neck squamous cell carcinomas also suggests that Notch1 may function as a tumor suppressor gene rather than an oncogene in this tumor." (PMID 23409141, 2013). "For example, the EphB2 receptor has been presented as a putative tumor suppressor gene in PCa, whereas the EphB4 receptor is known to be both tumor-promoting in the presence of its cognate ligand Ephrin B2 (EFNB2) and a tumor suppressor in the absence of EFNB2." (PMID 35565468, 2022). "Although downregulation of tumor suppresser WWOX expression has frequently been reported in various types of cancers, Wwox deletion did not necessarily increase the proliferation or development of premalignant lesions, suggesting that WWOX is not a classical tumor suppressor gene." (PMID 27234396, 2013).
cancer (197 papers, 2008 to 2026). A tumor composed of atypical neoplastic, often pleomorphic cells that invade other tissues. "S100A6 is an important calcium signal-regulating gene, and the calcium-binding protein it encodes is a member of the S100 family, which is associated with DNA damage and a variety of cancers." (PMID 36232318, 2022). "ARID1A, an SWI/SNF chromatin-remodeling gene, usually is mutated in cancer and is considered to be capable of suppressing tumors." (PMID 33771191, 2021). "XRCC2, a homologous recombination-related gene, has been reported to be associated with a variety of cancers." (PMID 34051735, 2021). "Supporting this it has been shown that in ~2.5% of all cancer, a germline mutation in a DNA repair gene was associated with cancer development." (PMID 32850380, 2020). "The B cell lymphoma/leukemia-2 gene (BCL2) and the Bcl2-associated X protein gene (BAX) are an oncogene and a cancer suppressor gene, respectively." (PMID 24459422, 2013). "Additionally, PSMD1 is classified as an innate immune gene, and its up-regulation is strongly associated with the progression of different types of cancers." (PMID 38933262, 2024). "Combined with our findings, PNPLA7 is likely to be a cancer suppressor gene that acts as a promising biomarker in various tumors." (PMID 40221501, 2025). "Mtss1 is well-known to act as a tumor suppressor gene in different types of cancer since it controls cell proliferation, migration, invasion and metastasis of cancer cells by regulating actin dynamics and signalling pathways." (PMID 41288860, 2025). "Conversely, senescent cancer cells treated with WEW exhibited an opposite effect on the expression of the pro-inflammatory gene." (PMID 38696307, 2024). "As a metastasis‐suppressor gene in many other cancers, SCN4B also inhibited the progression of LUAD." (PMID 37826914, 2023). "Recent studies have shown that most natural compounds reduce chemoresistance by inhibiting the expression of the multi-drug resistance gene (MDR) or reducing MDR protein activity in cancer cells." (PMID 36006482, 2023). "On the other hand, we also confirmed that p16 (a cancer suppressor gene) was a downstream target of H3K4me3, the promoter of which can directly bind to H3K4me3." (PMID 36866240, 2023). "MT1G is a DNA methylation-related gene which is reported to play an important role in various types of cancer." (PMID 35167648, 2022). "It acts as an oncogene in some cancers, while functioning as a cancer-suppressor gene in the other cancers." (PMID 36188536, 2022). "As a serine/threonine protein kinase, DAPK1 is considered to be a cancer suppressor gene, which is regulated by calmodulin (CaM) and is a positive regulator of IFN-γ-induced apoptosis." (PMID 35321516, 2022). "CCND1 was frequently overexpressed in various kinds of human cancers as a well-known cancer-related gene." (PMID 33996561, 2021). "XRCC1 is a DNA repair gene that plays a crucial role in maintaining genomic integrity and stability and in the pathogenesis and carcinogenesis of various type of cancer." (PMID 33868991, 2021).
cancer (continued). "Supporting our notion, CEP131 has been recently recognized as an important cancer-related gene in several human malignancies." (PMID 33014050, 2020). "Considering that the activity of this DNA repair gene is related to the progression of cancer, it is necessary to evaluate the DNA repair ability of cancer cells when chemotherapy is contemplated for cancer patients." (PMID 33261027, 2020). "Previous studies have shown that TXNIP is a cancer suppressor gene in numerous solid tumors and hematological malignancies." (PMID 33106166, 2020). "Approximately 10% of all cancers show a focal amplification of chromosome 1q21.2, a region harboring the antiapoptotic gene MCL1." (PMID 31266530, 2019). "KLF4 is a dual-function transcription factor, which can exert its role as an oncogene or a tumor suppressor gene depending on the cancer type or cancer stage." (PMID 30297986, 2018). "Studies have documented that activation of a DNA repair gene MTH1 is required for cancer cells to block incorporation of oxidized dNTPs and thereby prevent ROS-induced DNA damage." (PMID 28261604, 2017). "It is widely known that miRNA is important as an oncogene or a tumor suppressor gene depending on the subtypes of a particular cancer." (PMID 27304060, 2016). "Despite an increasing body of evidences is highlighting PATZ1 as a cancer-related gene, little is known about its function." (PMID 25595894, 2015). "This provide further evidence that miR-449a has a similar function to that of a cancer suppressor gene." (PMID 25202363, 2014). "Finally, we realized that COL11A1 has been identified as a potential metastasis-associated gene in other types of cancer as well, such as in lung, and oral cavity, suggesting that the MAF signature may be present in a subset of high stage samples of most if not all epithelial cancers." (PMID 21047417, 2010). "Given that both hypoxia and PLOD2 play critical roles in α-promoter-preferred DCLK1 activation, and that PLOD2 is a known a hypoxia-responsive gene in multiple cancers, we hypothesized that PLOD2 mediates hypoxia-induced activation of DCLK1-L." (PMID 40775208, 2025). "It has been identified as a cancer suppressor gene in some cancers." (PMID 38191448, 2024). "The novel pleiotropic gene WWOX is a cancer suppressor gene that could induce apoptosis and inhibit growth in various cancers." (PMID 38259487, 2023). "Serpine1 is a known hypoxia-sensitive gene, as reported in a previous study on cancer cells." (PMID 37432746, 2023). "Rad51, a DNA-repair-related gene, has been reported to be involved in multiple cancers." (PMID 34115569, 2021). "Studies suggested that Egr1 was a cancer suppressor gene and transcriptional regulator." (PMID 33479397, 2021). "MIF has been identified as a hypoxia-induced gene in cancer cells." (PMID 20727156, 2010). "In the first example, ERCC2 (also known as XPD) is a cancer-related gene." (PMID 20015360, 2009). "ATM, a DNA repair gene, is associated with various cancers but not previously linked to HCC." (PMID 41146957, 2025). "Finally, regarding the implications of p38β in cancer biology, it is important to mention that Stress Activated Protein Kinases signaling pathways, JNK and p38MAPK, have been shown to play a dual role in cancer, both as an oncogene and as a tumor suppressor gene." (PMID 33053909, 2020).
cancer (continued). "SMARCA1, a chromatin remodeling gene, has been reported to stimulate steroidogenic acute regulatory (StAR) protein expression through association with the StAR promoter, and SMARCA1 knockdown causes significant growth inhibition and induces apoptosis of cancer cells." (PMID 22272226, 2012). "The importance of balancing opposing activities in cancer is illustrated by genes such as HEF1 (NEDD9), a metastasis-related gene and HMMR, a gene involved in centrosome formation." (PMID 18636107, 2008). "In other cancers, MXRA5 has also been shown to be a cancer-promoting gene." (PMID 40002669, 2025). "Expression of Peg3, a growth-inhibitory imprinted gene which is frequently down-regulated in cancer, was absent (data not shown)." (PMID 20615237, 2010). "The growth-inhibitory imprinted gene Peg3 is not expressed by C26 cells, which is highly relevant since loss of Peg3 expression through promoter methylation, loss of heterozygosity and other mechanisms may stimulate clonogenic growth and contribute to the pathogenesis of a number of cancers." (PMID 20615237, 2010). "Using a novel genomic approach, we identified a 48-gene “Poised Gene Cassette” (PGC) showing tight regulation specifically in human cancers but not in corresponding nonmalignant tissues." (PMID 18636107, 2008).
infection (20 papers, 2006 to 2025). The state of being infected such as from the introduction of a foreign agent such as serum, vaccine, antigenic substance or organism. "In this study, we showed that another RpoS-regulated gene bb0689, as a novel virulence gene encoding an outer surface lipoprotein, contributes to the optimal infection of B. burgdorferi in animals." (PMID 39679711, 2025). "The homeobox gene egl-5 acted downstream of β-catenin/bar-1 to regulate the innate immune response to pathogenic infection." (PMID 36120363, 2022). "Its overexpression was shown to facilitate infection by rice black-streaked dwarf virus in Laodelphax striatellus (Fallén) through the suppression of the immune-related gene Ken." (PMID 40429173, 2025). "We also found that the SPβ-like phage Φ3T has a counter-defense gene that prevents SpbK-mediated abortive infection and enables the phage to produce viable progeny, even in cells expressing spbK." (PMID 40173202, 2025). "Increased direct antigen presentation compared to infection with the WT virus is achieved by deletion of the immune evasion gene m152 in virus mCMV-Δm152." (PMID 38149242, 2023). "In the present study, through the identification of the fungal virulence gene VdDpb4 from V. dahliae, we found that VdDpb4 is essential for the V. dahliae development and infection, including tolerant toward ROS stress during development and plant infection." (PMID 32298394, 2020). "The gene encoding PTS1 of C albicans and the cyb2 gene of C. glabrate were identified as a novel virulence gene or adaptive gene, respectively, in fungi based on screening the fungal mutants using the silkworm infection models." (PMID 28947778, 2017). "However, the salicylic acid-responsive defense gene and the jasmonic acid-responsive gene were induced more rapidly in Met-treated plants after infection with Pst and Bc, respectively." (PMID 38928022, 2024). "The discovery that production of these phytohormones is controlled by an hrp master regulatory gene whose activity is induced in presence of plant cells strongly suggests that these molecules play a key role during the early steps of infection in addition to the TTSS." (PMID 16933989, 2006). "Similar to results with lytic genes RTA, ORF49, K2 (vIL6), K14 (vOX2), ORF25, ORF36, latent gene LANA, or GFP, all lytic and latent genes expressed at higher levels following KSHV, as compared to KSHVΔLANA infection, at 72 hpi." (PMID 38232124, 2024). "A quantitative real-time PCR (qRT-PCR) assay was used to assess the expression of the Fov infection-related gene FOTG, and we found evidence of infection 28 h after inoculation." (PMID 30814537, 2019). "The infection of Sf9 cells revealed that deletion of the amino acids 91–173 of LEF-6 did not severely affect virus production, but the fluorescence intensity of GFP representing the expression of viral late gene was significantly reduced." (PMID 40787986, 2025). "GAPDH was used as a house-keeping gene, which displayed a non-coherent expression likely due to either the heterogeneous cell population found in the CP tissue or lower RNA integrities compared to RNA from the in vitro infection experiments." (PMID 33763387, 2021). "Taken together, this study has revealed that gene expression of the putative virulence gene B22R is a potential early marker of SGPV infection, detectable already after one day, and that hydrocortisone injection suppresses antiviral immune responses to SGPV during early infection." (PMID 34177946, 2021). "Harmine acted as an anti-infection agent mainly by inhibiting the transcription and expression of the T3SS regulatory gene hilA, and it did not affect S. Typhimurium growth." (PMID 36176578, 2022).
bacterial infection (1 paper, 2022). "Gene vom1 prevents the yolk from mixing with the albumen and protecting the egg from bacterial infection." (PMID 36498889, 2022).
ENSG00000280371 also shares sentences with these, for which no sentence is quoted: endometrial cancer (3 papers); nasopharyngeal carcinoma (3); Wilms tumor (3); acute lymphoblastic leukemia (2); Anxiety (2); cardiac arrhythmia (2); Cerebral ischemia (2); head and neck cancer (2); lymphoma (2); malaria (2); Multiple Myeloma (2); papillary thyroid cancer (2); psoriasis (2); retinal degeneration (2); Achalasia-Addisonianism-Alacrima syndrome (1); atherosclerosis (1); atrial fibrillation (1); benign tumors (1); blood disease (1); bone tumors (1); cervix (1); childhood leukemia (1); cholera (1); co-infection (1); Congenital adrenal hypoplasia (1); COVID-19 (1); cutaneous squamous cell carcinoma (1); dermatomyositis (1); diffuse astrocytoma (1); eczema (1).
A further 45 diseases each share a sentence with ENSG00000280371 in 1 paper.